ANKRD33 (ankyrin repeat domain 33)
Description:
Acts as a transcriptional repressor for CRX-activated photoreceptor gene regulation.
Synonyms: C12orf7; PANKY; DKFZp686O1689
Tractability: No criterion of Open Targets' tractability assessment is met for any kind of drug.
Gene: Protein-coding gene on chromosome 12 (51,888,009 to 51,891,727, forward strand). Ensembl gene ENSG00000167612.
Subcellular location: Cytoplasm, cytosol; Nucleus
Gene Ontology:
Cellular component: nucleus; cytosol
Genetic constraint (gnomAD): Loss-of-function variants: 25 observed, 25.85 expected, observed/expected ratio (o/e) 0.97, 90% interval 0.7 to 1.35. The upper end of that interval is the gene's LOEUF score, 1.35, which puts it in group 5 of 6, group 1 being the genes least tolerant of losing a copy. Missense variants: 545 observed, 589.52 expected, observed/expected ratio (o/e) 0.92, 90% interval 0.86 to 0.99. Synonymous variants: 246 observed, 251.25 expected, observed/expected ratio (o/e) 0.98, 90% interval 0.88 to 1.09.
Homologues: Orthologues: chimpanzee ANKRD33 (99% identical), macaque ANKRD33 (94% identical), dog ANKRD33 (66% identical), rat Ankrd33 (61% identical), mouse Ankrd33 (61% identical), rabbit ANKRD33 (61% identical), guinea pig ANKRD33 (52% identical), zebrafish ankrd33ab (33% identical), zebrafish ankrd33aa (31% identical). Paralogues in human: ANKRD33B (35% identical), FEM1A (17% identical), FEM1C (17% identical), FEM1B (14% identical).
Diseases named in the same sentence as ANKRD33 in open-access papers:
ANKRD33 is named in the same sentence as 2 diseases in open-access papers, as found by Europe PMC text mining. Sharing a sentence is not in itself a finding about the gene and the disease.
ANKRD33 shares sentences with these, for which no sentence is quoted: hyperglycaemia (1 paper); Insulin resistance (1).